TNF (tumor necrosis factor)
Diseases named in the same sentence as TNF in open-access papers (continued):
Sharing a sentence is not in itself a finding about the gene and the disease.
cancer (continued). "Overall, NSAIDs seem to have beneficial effects on cancer progression through their anti-inflammatory actions, but further research discussing the relationship among NSAIDs, TNF-α, and cancer prognosis should be executed." (PMID 36765695, 2023). "TNFα is recognized by a variety of stromal cells, mainly by TAMs, adipocytes, epithelial and malignant cancer cells themselves." (PMID 36835413, 2023). "Mycobacterium TB can induce the release of inflammatory mediators, e.g., tumor necrosis factor (TNF)-α and interleukin (IL)-1, IL-2, and IL-12, which can be viewed as cancer promotors." (PMID 37817103, 2023). "In parallel, TNFα was used as a representative of cancer inflammation, a process considered as prime inducer of cancer progression." (PMID 37190183, 2023). "The deletion of downstream genes in the TNF pathway promotes the cancer cells to escape from the killing by primary NK cells." (PMID 37427373, 2023). "Current laboratory data about the effect of propofol on the release of TNF-α in cancer cell biology are limited, and further investigations are required." (PMID 36765695, 2023). "The pathways regulated included T cell receptor, NF-κB, B cell receptor, chemokine, PD-L1 expression in cancer and PD-1 checkpoint, Toll-like receptor, TNF, JAK-STAT, NOD-like receptor, IL-17, apoptosis, PI3K-Akt, and other pathways." (PMID 37988189, 2023). "Laboratory research on the impact of lidocaine treatment on the release of TNF-α in cancer cell biology is limited." (PMID 36765695, 2023). "Although FasL and TNFα show potent cytotoxicity in cancer cells, the use of these DR agonists in the clinic has been jeopardized by their severe toxicity in normal cells and tissues." (PMID 37919293, 2023). "Our own studies confirm the influence of cytokines (i.e., concentrations of IL-1A, IL-1B, IL-2, IL-6, IL-10, TNF, and IL-4) on the emergence of fatigue in all its dimensions in patients with cancers of the reproductive organs at various stages of treatment." (PMID 36834426, 2023). "Cytokines such as tumor necrosis factor-alpha (TNF-α), interleukin-6 (IL-6), and IL-10 have been linked to cancer spread." (PMID 36771154, 2023). "The role of TNF-α in cancer cachexia is twofold: directly inducing catabolism in skeletal muscle through the activation of the Nuclear Factor Kappa B (NF-kB) pathway and promoting ubiquitin-mediated proteasome degradation of muscle protein." (PMID 37755304, 2023). "Pro-tumorigenic cytokines secreted by neutrophils and platelets (vascular endothelial growth factor, tumor necrosis factor-α, interleukin-10, etc.)contribute to cancer progression." (PMID 36979727, 2023). "Patients with anti-TNF inhibitors and biological drugs were tested on recurrent or new cancers but there was an overall median of 5.2 person-years of follow-up." (PMID 37954750, 2023). "In cancer, the expression of inflammatory signals, such as TNFα, IL-1β, and IL-6, are crucial indicators of sensitivity to chemotherapy and patient survival." (PMID 36672449, 2023). "Morphine-induced reduction of NFkβ and TNF-α leads to inhibition of tumor cell growth in a variety of cancer cells." (PMID 37765194, 2023). "The TNF-α, nuclear factor-kB (NF-κB), STAT3, AKT, and COX-2 are linked with different stages of cancer progression and reported to regulate cancer proliferation, apoptosis, invasion, metastasis, and angiogenesis." (PMID 38067358, 2023). "In particular, thiopurines, calcineurin inhibitors and anti-TNFα agents should be preventively discontinued during cancer therapy." (PMID 36672491, 2023). "On the other hand, miR-146a was related to cancer progression and metastasis because of its interactions with pathways linked to TNF-α (tumor necrosis factor-alpha) and TGF-β (transforming growth factor-beta)." (PMID 37998561, 2023).
cancer (continued). "The study aims to evaluate the effect of an ethanolic extract of Argemone mexicana Linn leaves on cancer-prevention and the expression pattern of TNF-α along with modulation of the p65 subunit of the NF-κB signalling pathway in the cancer-induced mouse model." (PMID 38067358, 2023). "An indirect way of determining the importance of TNF-α in the prognosis of cancer is by measuring TNF-α converting enzyme (TACE) activity." (PMID 36980727, 2023). "These pathways, which included the TNF signaling pathway, focal adhesion, proteoglycans in cancer, and complement and coagulation cascades, were mainly involved in LUSC." (PMID 38259849, 2023). "TNF-α is used as an immunostimulant drug, Tasonermin, in the treatment of certain cancers with modest effectiveness." (PMID 37534280, 2023). "The human clinical data of ACC and STAG showed that HDGF and TNFα acted inversely to produce cancer phenotypes." (PMID 37047540, 2023). "Last, we correlated CTNNB1 and TNF expression in the AMs of patients with cancer, highlighting the translational relevance of our findings." (PMID 37092550, 2023). "Lymphocytes release TNF, interferon-γ, and other cytokines, which can inhibit the growth and metastasis of cancer cells." (PMID 37554699, 2023). "Recently, it has been reviewed that IL6, TNFα, and IL1β play a central role in the toxicities of cancer immunotherapies." (PMID 36875156, 2023). "Herein, we endeavor to summarize the role of anesthesia in cancers from the insights of TNF-α release and subsequent cancer progression." (PMID 36765695, 2023). "TNF-α promotes cancer cell invasion via MMP9 production, which can remodel the extracellular matrix during metastasis." (PMID 37041137, 2023). "Patients with LGD IPMN, which is the least inflammatory stage of pre-cancer, have unaltered monocytes with proficient TNF responses to TLR stimulation." (PMID 37575220, 2023). "Astrocytes then secrete IL-6, TNF-α, IL-1β, IL-23, and other signalling molecules that promote cancer cell proliferation." (PMID 37056723, 2023). "Many cancer-related cytokines, such as IL-1β, IL-6, and TNF-α, are elevated during oral infections due to LPS stimulation." (PMID 37249977, 2023). "TNF contribution in the epithelial-to-mesenchymal transition (EMT) has also been reported in several cancer models, including renal, lung, and breast cell carcinoma." (PMID 38139369, 2023). "We found that in the co-culture of endotoxin-tolerant macrophages and cancer cells, the lower level of both IL-6 and TNFα cytokines was still observed." (PMID 37894480, 2023). "Further studies revealed that compound 39 would concentration-dependently inhibit TNF-α-induced NF-κB signaling in PC-3 cancer cells and lead to G2/M phase arrest of PC-3 cancer cells in the cell cycle." (PMID 37259376, 2023). "A tumor necrosis factor (TNF)-related apoptosis-inducing ligand (TRAIL) triggers apoptosis of cancer cells through DISC formation by binding to death receptors (DRs) and recruiting caspase-8 and FADD." (PMID 37628997, 2023). "Previous studies demonstrated the interconnection of SDF1/CXCR4 and TNF-α in cancer angiogenesis and metastasis." (PMID 36986504, 2023). "First, cancer cells stimulate an innate and aspecific response mediated by IL-1, IL-6, and TNF-alpha production; this kind of response mainly stimulates macrophages and neutrophil granulocytes to attack the tumor cells." (PMID 36900413, 2023). "This motif effectively shields cancer cells from the apoptosis-inducing effects of agents like cisplatin, etoposide, Tumor Necrosis Factor-alpha (TNF-alpha), and nitric oxide." (PMID 37892182, 2023). "Various cytokines such as IL-6 and TNF can increase catabolism and reduce albumin synthesis in cancer patients." (PMID 37143476, 2023). "Research in mouse models of cancer cachexia found that the anti-inflammatory cytokines TNFα and IL-6 were significantly inhibited, and the biochemical parameters were enhanced after the administration of oral L-carnitine." (PMID 36975525, 2023).
cancer (continued). "Although the anti-inflammatory effect of ketamine on the TNF-α release is predominated, the impact of ketamine administration in cancer surgery is still debated." (PMID 36765695, 2023). "TNF-α can induce necrosis of cancer cells yet facilitate a malignant phenotype by inducing the synthesis of matrix metalloproteinases." (PMID 38041080, 2023). "Cancer cells are less receptive to the stimulation of the antiviral response by interferons (IFNs) or tumor necrosis factor (TNF)." (PMID 37629483, 2023). "In cancer cells, TNF-α signaling is mediated via NF-κB and diverted from its role in cell death by RIPK1." (PMID 37516007, 2023). "In contrast, the PI3K-Akt signaling pathway and the TNF signaling pathway are involved in the regulation of the inflammatory response, which have been widely studied in cancer in recent years." (PMID 37543801, 2023). "Curcumin fights cancer by its action on various essential signaling molecules such as CDKs, NF-kB, tumor necrosis factor-alpha (TNF-a), and cyclooxygenase-2 (COX-2)." (PMID 37049544, 2023). "Consistent with this, we observed that TNFα-treated preadipocyte-conditioned media exhibited increased snail expression, mtROS, and the migratory capacity of cancer epithelial cells." (PMID 37107188, 2023). "Although both HM2 and D4 CAR T cells exhibited similar killing ability, D4 CAR T cells triggered 2- to 7-fold more secretion of cytokines including IFN-γ, IL-2, and TNF-α than HM2 CAR T cells after exposure to GPC1-positive cancer cells." (PMID 37031249, 2023). "The most therapeutically important EV ligands that have receptors on cancer cell surfaces are PD-L1, TNF, FasL, and TRAIL, and they are considered potential anti-cancer targets." (PMID 38203656, 2023). "TNFα potentiates EMT in several cancers by downregulating epithelial markers (e.g., E-cadherin) and stimulating the expression of mesenchymal markers." (PMID 36900285, 2023). "In comparison to acute infections, CD8+ T cells lose their ability to produce effector cytokines like interferon-γ (IFNγ) and tumor necrosis factor (TNF) when responding to progressive cancers and chronic infections." (PMID 37781382, 2023). "TNF-α, a multifunctional circulating cytokine, has been linked with a higher risk of CVD and a lower risk of overall and certain cancers." (PMID 37658860, 2023). "Fourteen out of 20 studies (70% of preclinical trials) assessed TNF-α levels in cancer models that received probiotics, and in 57% of the included studies (8 out of 14 studies), TNF-α declined significantly in probiotic-treated groups." (PMID 37719797, 2023). "For the part of inflammation in cancer, the following keywords were used: cytokines in cancer, inflammation in cancer, IL-6 in cancer, IL-10 in cancer, and TNF-α in cancer." (PMID 36771154, 2023). "Epidermal growth factor receptor (EGFR), transforming growth factor-beta (TGF-β), and tumor necrosis factor-alpha (TNF-α) ligands were reported for stimulating cancer cell progression and survival." (PMID 37893013, 2023). "With an increase in the number of patients with IBD and RA in higher age groups, it is assumed that more patients with carcinoma will be considered for the administration of anti-TNFα mAb." (PMID 36996146, 2023). "Helicobacter is a known pathogen and has also been linked with the elevation of IL1-β, tumor necrosis factor (TNF)-α expression, and carcinoma." (PMID 37375003, 2023). "Tumor necrosis factor-α (TNFα) is a key mediator of cytotoxicity that is frequently dysregulated in carcinoma and can be induced by a variety of chemo-, radio-, and immunotherapies." (PMID 36831373, 2023). "In MM there is an increased apoptosis of osteocytes, possibly due to the secretion of TNFα from cancer cells, as the anti-TNF antibody reversed osteocyte death." (PMID 35160258, 2022).
cancer (continued). "Many immune-related pathways, including the PD-L1 and PD-1 checkpoint pathway in cancer, as well as the T cell receptor signaling pathway and TNFα signaling pathway, were found to be enriched in circadian clock pathways." (PMID 35326729, 2022). "TNF-α in cancer-related fibroblasts and hepatic fibroblasts strongly triggers the IL-6 and MCP-1 expression levels, which in turn create a prometastatic microenvironment." (PMID 35954156, 2022). "Increased ROS was demonstrated to promote chronic inflammation, one of the major causes of cancer, through inducing chemokines such as IL-8 and CXCR4, as well as inflammatory cytokines including IL-1, IL-6 and TNF-α." (PMID 35740025, 2022). "The pathway enrichment analysis evaluate that genes were focused to EOC-associated signaling pathways: the ‘PI3K-Akt signaling pathway, proteoglycans in cancer, the TNF signaling pathway, and the IL-17 signaling pathway." (PMID 36145718, 2022). "The cancer related pathways enriched with downregulated genes include TNF signaling, JAK-STAT signaling, IL-17 signaling and NF-kappa B signaling pathways." (PMID 35672711, 2022). "In another pathway, the binding of FasL, TRAIL, or TNF-α induces cell death via death receptors (DRs) on the surface of cancer cells." (PMID 35721501, 2022). "In current immunotherapies for cancer, the TNF/TNFR2 pathway is critical for the suppression of Tregs." (PMID 35494080, 2022). "Proinflammatory factors such as IL-1, IL-6, IL-8, and TNFα generally enhance the occurrence and development of cancer by activating growth, metastasis, and invasion." (PMID 35443863, 2022). "Therapy with CGDCM resulted in a decrease in IL-6 and TNF-α expression, implying that the inflammatory signaling cascade is suppressed, slowing cancer progression." (PMID 35840761, 2022). "Other cancer clinical studies have used systemic administration of TNFα, demonstrating low efficiency and giving rise to multiple side effects." (PMID 35663982, 2022). "Like IL-6 and TNF-α, it is involved in cancer stromal activation, immune escape, angiogenesis, migration, and differentiation of many cell types and inhibition of apoptotic pathways." (PMID 36289922, 2022). "High HER2 level activates AKT, which triggers anti-apoptotic signaling to enhance the TNF-α resistance phenotype of cancer cells." (PMID 36338712, 2022). "In the 1970s, tumor necrosis factor (TNF) was systemically injected into patients with cancer as a cancer immunotherapy modality." (PMID 35936003, 2022). "In the proposed anti-cancer mechanism, statins inhibit the cell cycle proteins such as cyclins, the TNF-α synthesis, and the metastatic process by the downregulation of metalloproteinases." (PMID 35893743, 2022). "The tumor necrosis factor (TNF) superfamily member TNF-related apoptosis-inducing ligand (TRAIL) induces apoptosis in cancer cells via death receptor (DR) activation with little toxicity to normal cells or tissues." (PMID 36496977, 2022). "Enriched KEGG pathways included hematopoietic cell lineage, TNF signaling pathway, cytokine-cytokine receptor interaction, and transcriptional misregulation in cancer." (PMID 36277475, 2022). "Propranolol has some in vitro immunomodulating anti-cancer effects and it can reverse the epinephrine inhibition of TNF-alpha-mediated cytotoxic T lymphocyte generation." (PMID 36611747, 2022). "In human BC, upregulated TNF-α promoted the proliferation of the mammary gland cell line T47D and triggered several genes mediating cancer cells proliferation, invasion, and metastasis." (PMID 35955463, 2022). "Noteworthy, monocytes from patients with advanced cancer secreted significantly more TNFα than monocytes from patients at an early stage of the disease." (PMID 36498469, 2022). "Only BPV-E1^E4 transgenic cells were characterized by promoting and rewiring molecular programs based on the FoxO-, Rap1-, and TNF-mediated signaling pathways and molecular mechanisms dependent on proteoglycans actively functioning in cancer cells." (PMID 35216085, 2022).
cancer (continued). "This suggests that the elevation of CL-1 by TNF-α in tubular epithelial cells promotes cellular proliferation through the activation of cAbl, as also seen in cancer cells." (PMID 35271660, 2022). "MTT assay was carried out to assess the anticancer activity of cell-free synthesized human TNF-α against human cancer cell lines including Caco-2, HepG-2 and MCF-7." (PMID 35205024, 2022). "In the transcriptional level, cancer related cytokines including IL-1β, IL-6 and TNF-α were all reduced after IVM treatment." (PMID 36132145, 2022). "TNF is known to have both pro-survival and pro-death effects on cancer cells depending on its precise cellular context." (PMID 35401556, 2022). "It has been proven that as a result of the elimination of senescent cells, the level of proinflammatory cytokines, such as IL-1α, IL-6, and tumor necrosis factor α (TNFα), decreases, which prevents cancer relapse." (PMID 36232388, 2022). "The results showed that IL-6, IL-10, and TNF concentrations in the saliva of patients with cancer were significantly higher in the post-index group than in the pre-index group and significantly positively correlated with OM grade." (PMID 35476641, 2022). "CAFs release high levels of IL-6 and TNF-α in an autocrine fashion upon STAT3 activation when co-cultured with cancer cells, promoting self-renewal and metastatic potential of cancer cells." (PMID 35443745, 2022). "Alongside other cytokines, TNF-α is involved in the regulation of inflammatory processes, infectious diseases, and malignant tumors." (PMID 36289890, 2022). "We measured NF-κB p65 and TNF-α levels to evaluate the inflammatory response of the liver tissues adjacent to the cancer tissues." (PMID 36045714, 2022). "The high SCCA in malignant cells inhibited the serine protease and apoptosis, which induced by anti-cancer drugs, TNF-α and NK cells." (PMID 36275424, 2022). "The pro-survival effects of TNF-α on cancer cells, IL-6 overstimulation of Janus kinase/signal transducers and transcriptional pathway activators, and matrix metalloproteinases are thought to be mediated." (PMID 35752767, 2022). "In the cholangiocarcinoma model, treatment of both SMAC-mimetic (LCL161 and DEBIO1143) and TNF sensitizes cancer cells to a low dose of gemcitabine-induced necrosome complex formation and necroptosis upon the loss of cIAPs and caspase-8 function." (PMID 36361505, 2022). "Over the years, more extensive research that tried to employ Tumor Necrosis Factor in cancer treatments showed nevertheless that it mainly functioned as a proinflammatory cytokine." (PMID 36358688, 2022). "This counter-regulatory mechanism efficiently inhibits the potential anti-cancer and toxic effects of both TNF and NGR-TNF." (PMID 35890309, 2022). "MAPK signaling cascade activation increases the expression of inflammatory cytokines such as TNF-α and interleukin-8 in cancer." (PMID 35370699, 2022). "TNF has also been shown to have cancer-promoting effects in some cancer models, leading to several clinical trials of TNF antagonists demonstrating efficacy in some patients." (PMID 35401556, 2022). "Our findings suggest that TPL induces loss of FLIPS at the post-transcriptional level independently of proteasome-mediated pathway, an additional mechanism of TPL sensitizing cancer cells to TNF-α-induced apoptosis." (PMID 36308574, 2022). "The N1 phenotype with high levels of TNF-α, IL-2, IL-4, IL-7, and IL-10 expression induces a cytotoxic effect to cancer cells and hampers cancer cell progression." (PMID 35267547, 2022). "TNF-α, a widely expressed pleiotropic cytokine, is increased during inflammation and cancer in saliva and patient sera." (PMID 35484352, 2022). "Of interest, TRIB1 knockdown in MDMs (MTRIB1-KD) enhanced expression of IL1β and TNF mRNA, emphasizing that cancer cell secreted factors that were used to re-educate MTRIB1-KD to TAMTRIB1-KD are effectively altering the phenotypes of these cells." (PMID 35664073, 2022).